TBC1D25 (TBC1 domain family member 25)
Description:
Acts as a GTPase-activating protein specific for RAB33B. Involved in the regulation of autophagosome maturation, the process in which autophagosomes fuse with endosomes and lysosomes.
Synonyms: OATL1; MG81
Tractability: PROTAC: ubiquitination databases record sites on it; its protein half-life has been measured.
Gene: Protein-coding gene on chromosome X (48,539,684 to 48,562,609, forward strand). Ensembl gene ENSG00000068354.
Subcellular location: Cytoplasm; Cytoplasmic vesicle, autophagosome
Pathways (Reactome):
Vesicle-mediated transport: TBC/RABGAPs
Gene Ontology:
Molecular function: GTPase activator activity; protein binding
Biological process: regulation of autophagosome maturation
Cellular component: autophagosome; cytoplasm
Homologues: Orthologues: chimpanzee TBC1D25 (99% identical), mouse Tbc1d25 (94% identical), pig TBC1D25 (94% identical), rat Tbc1d25 (94% identical), guinea pig TBC1D25 (93% identical), rabbit TBC1D25 (86% identical), macaque TBC1D25 (84% identical), dog TBC1D25 (77% identical), zebrafish tbc1d25 (65% identical), Drosophila melanogaster CG8155 (41% identical). Paralogues in human: TBC1D16 (17% identical), RABGAP1 (15% identical), RABGAP1L (15% identical), TBC1D15 (15% identical), TBC1D4 (14% identical), TBC1D1 (14% identical), TBC1D17 (14% identical), TBC1D9 (14% identical), TBC1D10B (13% identical), TBC1D9B (13% identical), USP6NL (13% identical), TBC1D2 (13% identical), and 33 more.
Diseases named in the same sentence as TBC1D25 in open-access papers:
TBC1D25 is named in the same sentence as 14 diseases in open-access papers, as found by Europe PMC text mining. Sharing a sentence is not in itself a finding about the gene and the disease. The quoted sentences say what the papers report.
cardiac hypertrophy (1 paper, 2020). "Knockout of TBC1D25 aggravates interstitial fibrosis, myocardial dysfunction and cardiac hypertrophy." (PMID 32210723, 2020). "In order to illuminate the function of TBC1D25 in cardiac remodeling, we used TBC1D25-KO and their wild-type control mice to induce pathological cardiac hypertrophy by transverse aortic constriction (TAC)." (PMID 32210723, 2020). "To investigate the potential role of TBC1D25 in cardiac hypertrophy, we first analyzed the altered expression levels of TBC1D25 in pressure overload mouse heart." (PMID 32210723, 2020). "TBC1D25 knockout in mice leads to more severe myocardial fibrosis, cardiac dysfunction and hypertrophy." (PMID 32210723, 2020). "TBC1D25 expression was significantly increased in experimental cardiac hypertrophy, which indicated TBC1D25 may regulate pathological cardiac remodeling in this process." (PMID 32210723, 2020). "However, our present study showed that TBC1D25 is upregulated during the development cardiac hypertrophy and plays a very important role in this process." (PMID 32210723, 2020). "The results indicated that TBC1D25 could negative regulate myocardial fibrosis, cardiac dysfunction and hypertrophy." (PMID 32210723, 2020). "Knockout TBC1D25 exacerbated cardiac hypertrophy, fibrosis and dysfunction." (PMID 32210723, 2020). "The protective role of TBC1D25 in cardiac hypertrophy had been demonstrated." (PMID 32210723, 2020). "We next examined the contribution of TBC1D25 to cardiac hypertrophy in cardiomyocytes." (PMID 32210723, 2020). "Furthermore, we explored the molecular mechanisms by which TBC1D25 regulated cardiac hypertrophy." (PMID 32210723, 2020). "TBC1D25 could directly interact with TAK1 and significantly inhibit TAK1 phosphorylation in the development of cardiac hypertrophy." (PMID 32210723, 2020).
heart failure (1 paper, 2020). Inability of the heart to pump blood at an adequate rate to meet tissue metabolic requirements. "We conclude that TBC1D25 suppresses pathological cardiac remodeling via regulating TAK1-JNK/p38 signaling pathway, which suggests that TBC1D25 will likely become a promising therapeutic target for heart failure." (PMID 32210723, 2020).
ovarian tumor (1 paper, 2020). "In the library prepared from ovarian tumor tissue, 5 clones with coding sequences were identified using the HMGB1 bait (C1QA, DAG1, RPL29, RSF1, TGM2), and 6 (COMMD1, MIEN1, PCBP1, TBC1D25, ZFR, ZNF428) were identified with the HMGB2 bait." (PMID 32867128, 2020).
cancer (5 papers, 2014 to 2024). A tumor composed of atypical neoplastic, often pleomorphic cells that invade other tissues. "The least is known about the connection of TBC1D25 and cancer, but the protein is involved in the fusion of autophagosomes with endosomes and lysosomes, and was discussed in a study of mutations altering autophagy selectivity in human cancer." (PMID 35566209, 2022). "Analysing the top 100 co‐expressed genes of UBA1 in pan‐cancer on GEPIA2.0, the top 5 genes (CDK16, ELK1, KDM5C, RBM10 and TBC1D25) were highly correlated with UBA1 in most cancer types." (PMID 39183260, 2024). "The results showed that the mRNA levels of TBC1D1, TBC1D7, TBC1D8 and TBC1D14 significantly varied between different cancer stages, whereas the mRNA levels of TBC1D9b and TBC1D25 did not." (PMID 38766486, 2024). "The functions of TBC1D9b, TBC1D14 and TBC1D25 in cancer have not been well studied but are known to be closely related to autophagy." (PMID 38766486, 2024). "However, the functions of TBC1D25 in cancer development have not been explored." (PMID 34059679, 2021).
cardiovascular diseases (1 paper, 2020). "Additionally, the molecular mechanism of cardiac remodeling is extremely complicated, future studies are needed to elucidate the upstream of TBC1D25 in this process and clarify whether TBC1D25 participate in the development of other cardiovascular diseases." (PMID 32210723, 2020). "However, the role of TBC1D25 in cardiovascular diseases has not previously been investigated." (PMID 32210723, 2020).
tumor (1 paper, 2024). "In the present study, TBC1D9b, TBC1D14 and TBC1D25 were significantly overexpressed in HCC, and the expression levels of TBC1D9b, TBC1D14 and TBC1D25 were significantly correlated with HCC tumor grade." (PMID 38766486, 2024).
TBC1D25 also shares sentences with these, for which no sentence is quoted: Anxiety (1 paper); anxiety disorder (1); hypertrophy (1); melanoma (1); mood disorder (1); muscular dystrophies (1); Myocardial fibrosis (1); skin cutaneous melanoma (1).